NR2F2 (nuclear receptor subfamily 2 group F member 2)
Diseases named in the same sentence as NR2F2 in open-access papers (continued):
Sharing a sentence is not in itself a finding about the gene and the disease.
Sepsis (1 paper, 2023). Sepsis is defined as life-threatening organ dysfunction caused by a dysregulated host response to infection. "In a word, our study shows for the first time that the inactivation of NR2F2/miR128-3p/Snail1 pathway caused by the enhanced expression of ASLNC12002 is the direct reason why AECIIs in sepsis-induced ARDS patients are prone to get EMT progress." (PMID 36478088, 2023). "Although the role of NR2F2 has been explored in a few studies, our study is for the first time to analyze its role and mechanism in AECIIs of patients with sepsis-induced ARDS." (PMID 36478088, 2023). "In this study, to our knowledge, we for the first time showed that ASLNC12002 knockdown inhibited EMT of AECIIs in patients with sepsis-induced ARDS by reactivating the NR2F2/miR128-3p/Snail1 pathway." (PMID 36478088, 2023). "Mechanically, we identified that ASLNC12002 promotes EMT of AECIIs in patients with sepsis-induced ARDS by competitively binding to miR128-3p with Snail1 3’UTR and suppressing NR2F2/miR128-3p/Snail1 signal pathway." (PMID 36478088, 2023).
small cell ovarian carcinoma (1 paper, 2023). "COV434 cells, which were commonly considered as granulosa-like cells but recently reclassified as small cell ovarian carcinoma, did not express most granulosa markers, but did express high levels of WT1 and NR2F2." (PMID 36803359, 2023).
testicular cancer (1 paper, 2025). A primary or metastatic malignant neoplasm that affects the testis. "Further research is needed to clarify the role of Nr2f2 in testicular cancer." (PMID 40295478, 2025).
thyroid cancer (1 paper, 2026). "This therapy had surprising and promising results in our thyroid cancer study, further confirming the potential clinical value of targeting the NR2F2-BGN axis." (PMID 41328346, 2026). "Additionally, we established a murine thyroid cancer cell line model using the same experimental groups: control (pcdh+shNC), Nr2f2 overexpression (oe-Nr2f2+shNC), Bgn knockdown (pcdh+shBgn), and Bgn knockdown with Nr2f2 overexpression (oe-Nr2f2+shBgn)." (PMID 41328346, 2026).
tumor (53 papers, 2010 to 2026). "Meanwhile, NR2F2 has been implicated in maintaining tumor stem cell-like properties and upregulating genes involved in cell migration and invasiveness, facilitating tumor cells in breaching basement membranes and surrounding tissue barriers." (PMID 41614948, 2026). "Flow cytometry analysis of macrophage infiltration in mouse tumor tissues revealed that the Nr2f2-Bgn axis altered the proportion of tumor-associated macrophages (TAMs)." (PMID 41328346, 2026). "Furthermore, BGN knockdown partially reduced the tumor growth promotion caused by Nr2f2 overexpression." (PMID 41328346, 2026). "Tumor growth curves and tumor weight measurements revealed that Nr2f2 overexpression significantly promoted tumor growth, compared to the control group." (PMID 41328346, 2026). "Further experimental validation demonstrated that DHA treatment up-regulated NR2F2 and its target genes, suggesting that the anti-tumor effects of DHA are mediated through this regulatory axis." (PMID 39364872, 2025). "scRNAseq of tumor BECs confirmed selective expression of Nr2f2 by venular BECs in both PyMT and KPC tumors." (PMID 40796746, 2025). "For example, PARP3 (P = 0.4128) has been reported to contribute to tumor progression, and NR2F2 (P = 0.3383) has been identified as a critical regulator of malignant cancer stem cell functions." (PMID 40279344, 2025). "Identifying NR2F2 as a regulator of these genes positions it as a pivotal player in the anti-tumor activity of DHA." (PMID 39364872, 2025). "Treatment of PCa cells with dihydroartemisinin (DHA), an anti-tumor compound, significantly increased the expression of NR2F2, a transcription factor that directly binds to the EBF1 promoter and activates its transcription." (PMID 40508012, 2025). "Although the independent anti-cancer role of EBF1 was not explicitly dissected in this study, its involvement in the NR2F2 regulatory network indirectly supports its tumor-suppressive role in PCa." (PMID 40508012, 2025). "Recent research indicates the potential roles of NR2F2 in the progression of LAM due to its overexpression in tumor tissues." (PMID 39311119, 2024). "Nr2f2 modulates the metastasis of breast tumor cells to the lungs by activating the expression of Ang1, thereby promoting tumor angiogenesis, facilitating the provision of nutrients and oxygen to support tumor cell metastasis to the lungs." (PMID 39311119, 2024). "In metastatic lung cancer, NR2F1 mainly inhibits the transition of dormant tumor cells to a proliferative state in the lungs, while NR2F2 influences tumor cell metastasis to the lungs by affecting the tumor microenvironment, such as angiogenesis or EMT." (PMID 39311119, 2024). "Comparing the expression of the CDDP-DTP-associated genes between tumor and normal adjacent tissue, and its clinical relevance, we found that six (GADD45A, SOCS1, EPS15, GLI3, NR2F2, and RCOR1) of the hub genes have significant differences." (PMID 37916165, 2023). "A recent study demonstrated that Wnt/NR2F2/GPX4 promoted acquired chemoresistance by suppressing ferroptosis with high consumption of GSH, and also revealed the key role of NR2F2 in the regulation of tumor metabolism." (PMID 36465351, 2022). "In conclusion, we confirmed that Fbxo21 played a crucial role in tumor growth, metastasis and prognosis via Nr2f2/Snail pathway." (PMID 33531987, 2021). "In contrast, conditional ablation of NR2F2 severely compromised neoangiogenesis and suppressed tumor growth in xenograft mouse model." (PMID 32631390, 2020). "The expression of NR2F2 in terminally differentiated epithelial cells functions in mesenchymal-endothelial interactions, angiogenesis, tumor growth and metastasis by inhibiting TGF-β-induced growth." (PMID 27844448, 2017). "The TGF-β/SMAD4 dependent barrier to tumor progression is destructed in metastatic PCa through involvement of transcription factor COUP-TFII/NR2F2." (PMID 25277175, 2014).
tumor (continued). "In cancer, the role of NR2F2 is controversial, as it may act as both an oncogene and a tumor suppressor gene." (PMID 41328346, 2026). "Tumor growth curves and tumor weight measurements showed that NR2F2 overexpression significantly promoted tumor growth, while BGN knockdown partially inhibited the tumor growth promotion caused by NR2F2 overexpression." (PMID 41328346, 2026). "This suggests that CIA1 may regulate macrophage polarization and the tumor immune microenvironment through targeting the NR2F2-BGN axis, providing a potential foundation for its therapeutic application in PTC." (PMID 41328346, 2026). "Furthermore, we explored the enhancer-dependent transcriptional regulation of BGN by NR2F2, elucidating how the NR2F2-BGN axis contributes to tumor progression and immunosuppressive microenvironment formation." (PMID 41328346, 2026). "NR2F2 can regulate tumor growth and metastasis by regulating tumor angiogenesis." (PMID 36011369, 2022). "NR2F2 is reported to be closely related to tumor metastasis and metastasis regulation." (PMID 34084171, 2021). "NR2F2 is also observed in tumor infiltrating tissue and participates in metastasis regulation." (PMID 34084171, 2021). "Moreover, a prior study demonstrated that NR2F2 could play an important role in tumorigenesis by regulating multiple signalling pathways and controlling tumour cell growth and angiogenesis." (PMID 39219375, 2024). "Treatment with the NR2F2 inhibitor CIA1 blocks NR2F2 activation of BGN, reducing BGN expression and AKT pathway activity, inhibiting malignant behavior of tumor cells, and reversing macrophage polarization, thereby restoring antitumor immunity." (PMID 41328346, 2026). "We found that NR2F2 directly binds to both the BGN enhancer and promoter regions, activating BGN transcription, thereby driving PTC tumor progression and the formation of an immunosuppressive microenvironment." (PMID 41328346, 2026). "This study revealed the mechanism by which NR2F2 promotes BGN transcription and tumor progression in PTC." (PMID 41328346, 2026). "Immunohistochemical analysis of tumor tissues further revealed a positive correlation between Ki67 and p-AKT expression levels and NR2F2-BGN axis activity." (PMID 41328346, 2026). "In previous work, it was demonstrated that NR2F2 can bind to and activate the BGN promoter and enhancer regions, promoting its expression and facilitating tumor progression and the formation of an immunosuppressive microenvironment." (PMID 41328346, 2026). "By identifying NR2F2 as a central regulator, we provide a deeper understanding of how DHA modulates key genes and pathways involved in tumor progression." (PMID 39364872, 2025). "NR2F2, the nuclear receptor subfamily 2, group F, member 2, regulates a whole of important signal pathways, and NR2F2 is one of the main regulatory factors in EMT and closely related to invasion and migration of tumor and poor prognosis of patients." (PMID 36478088, 2023). "In contrast, the expressions of SOCS1, EPS15, GLI3, NR2F2, and RCOR1 were significantly decreased in tumor compared to normal tissue (p < 0.05)." (PMID 37916165, 2023). "According to the RNA-seq analysis, NRP2, NODAL, and NR2F2 were highly expressed, while EGF was lowly expressed in tumour tissue." (PMID 36172369, 2022). "The nearby protein‐coding gene of SCDAL is the nuclear receptor subfamily 2 group F member 2 (NR2F2, also known as COUP‐TFII) gene, which serves as a known regulator in tumor angiogenesis." (PMID 34319658, 2021). "Marker genes differentially expressed in the blastemal tumours relative to triphasic tumours included CM (EYA1, HOXA10, NR2F2) and PA (WT1) genes." (PMID 29040332, 2017). "To explore the relationship between promoter methylation and gene expression in primary tumours we performed a qRT-PCR analysis of SOX9, HOXA9, AHR, ROBO1, and NR2F2 in a series of 36 MCL." (PMID 21603610, 2011).
tumor (continued). "The subsequent analysis in primary MCL identified five genes (SOX9, HOXA9, AHR, NR2F2, and ROBO1) frequently methylated in these tumours." (PMID 21603610, 2011). "In conclusion, our study not only reveals a novel enhancer-mediated transcriptional mechanism involving NR2F2 and BRD4 that activates BGN in PTC but also highlights BGN's dual role in promoting tumor cell-intrinsic aggressiveness and shaping the tumor immune environment." (PMID 41328346, 2026). "Mechanistically, RNA sequencing results suggest LCFAs may primarily suppress tumor progression through the transcriptional regulation of MSX1, CEBPG, and NR2F2." (PMID 41614948, 2026). "Immunohistochemical analysis of tumor tissues demonstrated that CIA1 treatment downregulated BGN, Ki67, and p-AKT expression, while NR2F2 and total AKT levels remained unchanged, suggesting that CIA1 primarily acts through inhibition of the NR2F2-BGN axis." (PMID 41328346, 2026). "Tumor growth and metastasis were inhibited in a spontaneous mammary-gland tumor model in the absence of NR2F2 by regulation of angiopoietin-1." (PMID 32631390, 2020). "Besides, new methods such as GWAS, which located a new gene NR2F2 involved in LAM, and systems biology approach, which found the correlation of mTOR with DNA damage checkpoint, used in tumor research could help open minds in studying new targets, which, however, need to be further validated." (PMID 33072782, 2020).
cancer (45 papers, 2009 to 2026). A tumor composed of atypical neoplastic, often pleomorphic cells that invade other tissues. "For example, we observed that ESR1 and NR2F2, two TFs that are highly mutated in various types of cancer, cooperatively bind to 10 different promoters in our network." (PMID 39013578, 2024). "Our bioinformatics analysis revealed distinct expression patterns of the NR2F2 gene set across various cancers, suggesting its involvement in diverse molecular pathways." (PMID 39364872, 2025). "We used NR2F2 depleted WJ-MSCs co-cultured with HepG2 and HCT116 cells and found that NR2F2 depleted WJ-MSCs can affect the proliferation and apoptosis of cancer cells." (PMID 36011369, 2022). "As a regulator of transcription, Nr2f2 plays an important role in many pathological and physiological processes, including organ development, metabolism, and cancer." (PMID 36081650, 2022). "Studies have shown that WJ-MSCs can inhibit the growth of cancer cells since we observed that NR2F2 in WJ-MSCs can affect various signaling pathways such as intercellular adhesion, cell chemokines, and cytokine receptors." (PMID 36011369, 2022). "No prior publications were found describing the effects of insulin on the expression level of NR2F2 in cancer cells." (PMID 32631390, 2020). "The opposing effects of NR2F2 expression on cancer cell growth and metastasis indicate the complexity of its role in cancer." (PMID 32631390, 2020). "For instance, MAP3K8, MAP3K13, NCF2, NF-κB (family), NFATC2, NF-κB (complex), and NR2F2 were significantly disturbed by myricetin treatment, which are belonging to cancer related MAPK/NF-κB inflammatory signaling pathway." (PMID 30956980, 2019). "The network is apparently related to oxidative stress (Nr2f2), cancer (Jun, Kras) and metabolic pathways (ApoE)." (PMID 23922661, 2013). "Among the genes encoding zinc ion-binding proteins, three (ANPEP, LIMCH1 and NR2F2) are known to be cancer-related." (PMID 21209903, 2010). "NR2F2 influences various cellular processes, including proliferation, differentiation, apoptosis, and metabolism, and plays a role in striated muscle development and various cancers." (PMID 39364872, 2025). "To test this conjecture, we co-cultured WJ-MSCs in the Control RNAi group and WJ-MSCs in the NR2F2 RNAi group with HepG2 and HCT116 cells, respectively, to observe whether NR2F2 played a role in the inhibition of cancer by WJ-MSCs." (PMID 36011369, 2022). "As in our study, the RNA-seq results showed that PDGFRA was down-regulated, TGFBR2 was up-regulated, and the expression of related apoptosis markers was increased after NR2F2 knockdown, suggesting that NR2F2 promotes the effect of WJ-MSCs in inhibiting cancer cell proliferation." (PMID 36011369, 2022). "The downregulation of NR2F2 inhibits cancer cell proliferation and EMT." (PMID 36011369, 2022). "Therefore, clarifying the molecular mechanism by which NR2F2 regulates the growth of WJ-MSCs and exerts anti-cancer effects is beneficial to deepen the understanding of WJ-MSCs and provide new ideas for cancer treatment." (PMID 36011369, 2022). "In addition to its role in cancer, there are also related studies on the stemness regulatory function of NR2F2." (PMID 36011369, 2022). "Our fourth aim was to probe the possible anti-cancer properties of NR2F2." (PMID 36011369, 2022). "Importantly, we speculated that NR2F2 might also play a role in the inhibition of cancer cell growth by WJ-MSCs." (PMID 36011369, 2022). "Among these, NR2F2 (COUP-TFII) emerged as a central hub gene and a transcription factor, suggesting its critical role in regulating downstream genes involved in cancer progression." (PMID 39364872, 2025). "Hence, NR2F2 may play a direct role in a variety of cancer cells." (PMID 36011369, 2022).
cancer (continued). "We also utilized a co-culture system in which NR2F2-depleted WJ-MSCs with MH7A and HCT116/HepG2 were used to investigate the role of NR2F2 in immunomodulation and the inhibition of cancer cell growth." (PMID 36011369, 2022). "The top 5 important TFs observed in more than 10% of all cancer genomes include SP1, RXRA, NR2F2, GABPA, and CTCF." (PMID 33647036, 2021). "Moreover, GPX4 has been identified as a critical survival protein for cancer cells in a high mesenchymal therapy‐resistant cell state in the antilipid peroxidase pathway 14, 23 while there is a paucity of studies investigating the effects of NR2F2 on drug resistance." (PMID 34586745, 2021). "The nuclear receptor subfamily 2, group F, member 2 (NR2F2) is a master regulator of angiogenesis and acts as oncogene in prostate and other human cancers." (PMID 28210221, 2017). "Furthermore, the use of the NR2F2-specific inhibitor CIA1 in our study shows promising therapeutic potential, further supporting the clinical value of targeting the NR2F2-BGN axis in cancer treatment." (PMID 41328346, 2026). "NR2F2 and NR2F6 are members of the nuclear receptor (NR) superfamily that has been a source of therapeutic targets for the treatment of several diseases, including cancers." (PMID 37370765, 2023). "Concerning transcription factors, sets of the most important features are less similar to each other for different cancer types but nevertheless CTCF, GABPA, RXRA, SP1, MAX and NR2F2 are more frequently included in top features than other transcription factors." (PMID 33647036, 2021). "Moreover, reduced Fbxo21 expression promoted cancer cell proliferation, migration and invasion, especially the EMT partially through Nr2f2 signaling pathway." (PMID 33531987, 2021). "The results showed that the protein expression of Nr2f2 in cancer tissues was significantly higher than that in normal tissues." (PMID 33531987, 2021).
neurodevelopmental disorder (2 papers, 2021 to 2024). A behavioral and cognitive disorder with onset during the developmental period that involves impaired or aberrant development of intellectual, motor, or social functions. "This is consistent with previous findings on involvement of NR2F1 and NR2F2 in development of different brain structures in various animal models, regulation of neurodevelopmental timing, and their association with neurodevelopmental disorders in humans." (PMID 38177910, 2024).
NR2F2 also shares sentences with these, for which no sentence is quoted: metabolic disease (5 papers); prostate tumor (5); cardiomyopathy (4); colon cancer (4); atrioventricular septal defect (3); dilated cardiomyopathy (3); hypogonadism (3); infection (3); lung adenocarcinoma (3); pancreatic cancer (3); cardiovascular diseases (2); cervical cancer (2); Duchenne muscular dystrophy (2); Glucose intolerance (2); Hyperinsulinemia (2); Hypertension (2); Hypoglycemia (2); injury (2); lymph node metastasis (2); Micropenis (2); muscular dystrophy (2); periodontitis (2); pulmonary hypertension (2); viral pneumonia (2); acute kidney injury (1); acute myeloid leukemia (1); adenomyosis (1); adrenal hypoplasia congenita (1); anemia (1); aortic coarctation (1).
A further 44 diseases each share a sentence with NR2F2 in 1 paper.